FST (follistatin)
Diseases named in the same sentence as FST in open-access papers (continued):
Sharing a sentence is not in itself a finding about the gene and the disease.
dysferlinopathy (1 paper, 2021). "When transgenic overexpression of follistatin (F66-mice) is crossed with the dysferlinopathy LGMD2B model Dysf−/−, the positive effect on muscle weight in F66;Dysf−/−-mice declines with age and the specific force of EDL is reduced, compared to F66-mice, exacerbating the dystrophic phenotype." (PMID 33802348, 2021). "The authors conclude that follistatin overexpression accelerated the degenerative features in the dysferlinopathy model, as the dystrophin-deficient mdx was not exacerbated, and suggest that muscle hypertrophy may have pernicious effects depending on the disease context." (PMID 33802348, 2021).
endothelial dysfunction (1 paper, 2022). In vascular diseases, endothelial dysfunction is a systemic pathological state of the endothelium (the inner lining of blood vessels) and can be broadly defined as an imbalance between vasodilating and vasoconstricting substances produced by (or acting on) the endothelium. "PCOS per se has been viewed as a state of chronic low-grade inflammation with increased production of specific cytokines and chemokines such as TNFα, IL-1, IL-6, follistatin, CRP, and adhesion molecules involved in endothelial dysfunction." (PMID 35564864, 2022).
esophageal cancer (1 paper, 2015). A primary or metastatic malignant neoplasm involving the esophagus. "Of the angiogenic factors VEGF, Angiopoietin-2, PECAM-1, Follistatin, Leptin, G-CSF, HGF, PDGF-BB and IL-8, two angiogenic factors (HGF and Follistatin) are associated with esophageal cancer patients’ prognosis in posttherapeutic tumor tissue." (PMID 25885021, 2015). "In this study two angiogenic factors (HGF and Follistatin) in tumor tissue after neoadjuvant therapy were associated with esophageal cancer patients’ prognosis." (PMID 25885021, 2015). "Two angiogenic factors (HGF and Follistatin) in posttherapeutic tumor tissue are associated with prognosis in esophageal cancer patients." (PMID 25885021, 2015). "Expression levels of most angiogenic factors in AEG and SCC were similar, biological differences of these two entities of esophageal cancer with respect to angiogenesis are indicated by the different expression of Angiopoietin-2 and Follistatin." (PMID 25885021, 2015). "Elevated levels of Follistatin as an antagonist of the TGFβ superfamily member Activin A have been reported in solid tumors, however no data on esophageal cancer have been published so far." (PMID 25885021, 2015).
gestational diabetes (1 paper, 2014). Carbohydrate intolerance first diagnosed during pregnancy. "Regarding follistatin determinants, circulating levels were negatively associated with maternal age, HOMA-IR index and the diagnosis of gestational diabetes, and positively with triglycerides concentrations." (PMID 24763182, 2014). "Also, in the stepwise multiple linear regression analysis serum follistatin levels were negatively associated with HOMA-IR (β = −0.199, P = 0.008) and the diagnosis of gestational diabetes (β = −0.138, P = 0.049)." (PMID 24763182, 2014). "However after controlling for other confounding factors the diagnosis of gestational diabetes remains a negative determinant of serum follistatin concentrations, leading us to suggest a possible role of follistatin in the carbohydrate metabolism during pregnancy." (PMID 24763182, 2014).
glaucoma (1 paper, 2025). Increased pressure in the eyeball due to obstruction of the outflow of aqueous humor. "Luminex analysis of AqH samples revealed significantly elevated levels of MMP-2, MMP-3, ET-1, sEMMPRIN, ZAG, sLOX-1, follistatin, cortisol, endostatin, sTIE-2, and PDGF-BB in glaucoma participants (adjusted p < 0.05)." (PMID 41154592, 2025).
Granulosa cell tumours (1 paper, 2023). "Whereas, Granulosa cell tumours showed enrichment of antagonism of Activin and Follistatin in the Indian Cohort." (PMID 37091785, 2023).
H1N1 Influenza (1 paper, 2014). "This study establishes that in critically ill patients with severe H1N1 Influenza, the levels of activins A, B and follistatin are elevated in a significant proportion of patients." (PMID 24885241, 2014).
head and neck cancer (1 paper, 2024). A primary or metastatic malignant neoplasm affecting the head and neck. "We delve deeper into the expression patterns and mechanistic role of follistatin in cancer, examining its intimate relationship with TGF-β and its implications in drug resistance across lung, ovarian, and head and neck cancers." (PMID 38392348, 2024).
hyperandrogenism (1 paper, 2022). Excessive secretion of androgens from the adrenal glands or gonads. "Additionally, a strong association between follistatin and the Cytochrome P450 Family 11 Subfamily A Member 1 (CYP11A1) gene in affected siblings with hyperandrogenism and PCOS related traits was predicted by studying 37 candidate genes." (PMID 35787810, 2022).
infarction (1 paper, 2017). A localised pathological necrosis of tissue resulting from obstruction of the blood supply usually by a thrombus, an embolus, or vascular torsion. "The expression of activin A, follistatin, caspase-3, and CHOP increased obviously in infarction and noninfarction areas of the myocardial tissue in rats with eight-week MI." (PMID 28208629, 2017).
infiltrating ductal carcinomas (1 paper, 2009). "In high grade infiltrating ductal carcinomas (IDC), FST expression pattern was not altered, while FLRG expression was increased in the same tumor." (PMID 19740438, 2009).
Iron Deficiency (1 paper, 2023). "The mRNA expression of the endometrium receptivity-related genes, PR, SOX-17, CX3CR1, FKN, activin, follistatin, BMP2, as well as the examined cytokines and chemokines LIF, IL-6, and IL-1β, were significantly downregulated at DFO-induced iron deficiency in HEC-1A cells." (PMID 37175630, 2023).
ischemia reperfusion injury (1 paper, 2024). Adverse functional, metabolic, or structural changes in ischemic tissues resulting from the restoration of blood flow to the tissue (reperfusion), including swelling; hemorrhage; necrosis; and damage from free radicals. "Although previous studies have reported that urinary activin is detected in mouse models with ischemia-reperfusion injury and human AKI, correlating with renal injury severity, whether urinary follistatin is present in AKI patients remains uncertain." (PMID 38534369, 2024). "While a strong correlation was observed between urinary follistatin and urinary KIM-1 in a rat model of ischemia-reperfusion injury, urinary follistatin did not correlate with KIM-1 in our human study." (PMID 38534369, 2024).
keloid (1 paper, 2024). An irregularly shaped, elevated mark on the skin caused by deposits of excessive amounts of collagen during wound healing. "NKs, KKs, NFs, and KFs express different levels of activins and follistatin (an inhibitor of activins), and their interaction can affect the pathogenesis of keloids." (PMID 38279232, 2024).
meningitis (1 paper, 2016). A disorder characterized by acute inflammation of the meninges of the brain and/or spinal cord. "The levels of mRNA and secreted protein have been reported to be reduced for follistatin in peripheral blood mononuclear cells of relapsing-remitting multiple sclerosis (MS) patients, while the CSF level of follistatin protein is increased during meningitis." (PMID 26914813, 2016).
metastatic disease (1 paper, 2017). "It is well established that the immunoreactivity can enhance tumor growth and metastatic disease, and we expect that any immunomodulatory impact of FST/activin should be observed in this model." (PMID 28583174, 2017).
muscle atrophy (1 paper, 2015). The loss of muscle tissue due to inactivity or disease. "Additionally, it will be important to investigate whether follistatin-based interventions could be combined with other approaches that circumvent the signalling effects of denervation, to develop superior therapies for muscle atrophy." (PMID 26657343, 2015).
muscle disorders (1 paper, 2022). "We further characterized the role of fsta in the vasculature that has not been reported before, although many studies have shown that follistatin functions in skeletal muscle development and growth and even shows potential medical applications for muscle disorders." (PMID 35740282, 2022).
myeloma (1 paper, 2015). "Thus, the ratio between follistatin and activin A should determine activin A’s ability to inhibit BMP-6 or BMP-9, both with regards to myeloma cell apoptosis and to osteoblastogenesis." (PMID 26047946, 2015).
myopia (1 paper, 2024). "The follistatin gene changed in both mouse and chick retinas and has also been implicated in human myopia." (PMID 39876870, 2024).
myositis (1 paper, 2020). "We have seen that some of myokines, as follistatin and Insl6, have a low expression in myositis, intense exercise being already a good modulator, so as to induce their overexpression for the benefit of muscle tissue." (PMID 32775472, 2020).
Nephropathy (1 paper, 2024). A nonspecific term referring to disease or damage of the kidneys. "Activin A is known to impede tubular repair following renal ischemia, whereas exogenous follistatin, an activin A antagonist, has been shown to ameliorate kidney damage in rats." (PMID 38534369, 2024). "Conversely, in cases of AKI progressing to irreversible ESRD due to contrast-induced nephropathy or cholesterol crystal embolism, elevated levels of urinary follistatin persisted until discharge." (PMID 38534369, 2024).
neuropathic pain (1 paper, 2016). Chronic pain caused by damage to nerve fibers. "Of the 47 investigated proteins, 21 (cathepsin S, CCL2, CCL4, CCL16, CFIII, CXCL5, cystatin B, E-Selectin, Fas/TNFRSF6, follistatin, GDF-15, GH, ICAM1, IL8, KLK5, MMP2, MMP9, P-Selectin, sortilin, TIMP4 and VEGF) were detectable by multiplex SP-PLA in ≥ 95% of the neuropathic pain patient samples." (PMID 26914813, 2016).
orofacial cleft (1 paper, 2024). A disorder of facial skeleton that is characterized by cleft lip and/or cleft palate that result in feeding, speech and hearing problems caused by failures during development. "This function of FST is further substantiated by exome sequencing-based studies revealing a mutant variant of FST that impedes interaction with GDF11, a TGF-β family member, resulting in orofacial clefts in human patients akin to FST-null mice." (PMID 38392348, 2024).
Ovarian cyst (1 paper, 2016). The presence of one or more cysts of the ovary. "Interestingly, it has been found recently, that the expression of the components of the activin–inhibin–follistatin system is also altered in bovine ovarian cysts, thus suggesting the initiation of similar unfavorable processes within the dominant follicle by acute pre-ovulatory heat stress." (PMID 27532452, 2016).
ovarian disorder (1 paper, 2022). A disease involving the ovary. "As important regulators in reproduction, activin-inhibin-follistatin system has been associated with some ovarian disorders in humans." (PMID 36469526, 2022).
ovarian mucinous tumor (1 paper, 2014). "Previous studies have revealed that serum FST served as a biomarker for pregnancy and ovarian mucinous tumor." (PMID 25347573, 2014).
papilloma (1 paper, 2017). A benign epithelial neoplasm that projects above the surrounding epithelial surface and consists of villous or arborescent outgrowths of fibrovascular stroma. "Concomitantly, mRNA levels of follistatin were mildly reduced in the papillomas (Fig EV1A), suggesting that the overexpressed activin is functionally active." (PMID 27932444, 2017).
postmenopausal osteoporosis (1 paper, 2023). Metabolic disorder associated with fractures of the femoral neck, vertebrae, and distal forearm. "Therefore, higher follistatin concentrations in women with postmenopausal osteoporosis were thought to be compensatory in order to restrain bone loss." (PMID 37508723, 2023).
prediabetes (1 paper, 2018). "In conclusion, activin A level, but not follistatin, was elevated independent of demographic variables with borderline significance and was correlated positively with cIMT in prediabetes." (PMID 29967428, 2018). "In conclusion, circulating activin A levels, but not follistatin levels, increased in subjects with prediabetes independent of demographic parameters with borderline significance." (PMID 29967428, 2018). "We have advanced knowledge in this area by further showing that activin A levels, but not follistatin levels, increased in subjects with prediabetes independent of demographic variables with borderline significance." (PMID 29967428, 2018).
preeclampsia (1 paper, 2023). Preeclampsia is a hypertensive disorder of pregnancy that is characterized by new-onset hypertension with proteinuria presenting after 20 weeks of gestation, and depending on mild or severe forms may initially present with severe headache, visual disturbances, and hyperreflexia. "In the last decade, assessments of maternal serum levels of the activin-inhibin-follistatin system proteins disclose both subtle and significant changes across preeclampsia." (PMID 37595293, 2023). "Serum follistatin levels are reduced in women with preeclampsia during the late second and third trimesters." (PMID 37595293, 2023). "Follistatin serum levels in women with preeclampsia are significantly reduced at the late second and third trimesters (25+0–40+0 weeks of gestation), though changes in maternal serum follistatin-like 3 remain uncertain." (PMID 37595293, 2023). "The records gathered in the present review display the findings of the investigations into the activin-inhibin-follistatin system in preeclampsia in the last ten years." (PMID 37595293, 2023). "Only one study has evaluated follistatin variation in mild preeclampsia prediction in the late second and third trimesters in the past decade, with an AUC of 0.771 when measured between the 25+0–40+0 weeks of gestation." (PMID 37595293, 2023). "Within the endocrine-paracrine signalling network at the maternal-foetal interface, the activin-inhibin-follistatin system modulates extravillous trophoblast invasion, suggesting a potential role in preeclampsia pathogenesis." (PMID 37595293, 2023). "Moreover, serum follistatin levels in women with preeclampsia are significantly reduced in the late second and third trimesters." (PMID 37595293, 2023).
sarcoidosis (1 paper, 2015). Sarcoidosis is a multisystemic disorder of unknown cause characterized by the formation of immune granulomas in involved organs. "In the sarcoid patients concentrations of serum Ang-2, follistatin, GM-CSF, IL-8, PDGF-BB, PECAM-1 and VEGF were similar to the values noticed in the control group." (PMID 26438257, 2015). "In the sarcoidosis group we found statistically significant relationships between concentrations of Ang-2 and IL-8 (r = 0.62, P < 0.0001), follistatin and PECAM-1 (r = 0.76, p < 0.0001) as well as PDGF-BB and PECAM-1 (r = 0.82, p < 0.0001)." (PMID 26438257, 2015). "To the best of our knowledge we were the first to demonstrate the serum concentrations of Ang-2, PECAM-1 and follistatin in IPF and sarcoidosis." (PMID 26438257, 2015). "In our study elevated serum concentrations of IL-8, GM-CSF, follistatin, PDGF-BB and PECAM-1 in the IPF patients, but not in the sarcoidosis patients even in active progressive disease have been observed." (PMID 26438257, 2015). "We observed an increased serum concentration of follistatin in IPF, but not in sarcoidosis." (PMID 26438257, 2015).
seminoma (1 paper, 1997). A radiosensitive malignant germ cell tumor found in the testis (especially undescended), and extragonadal sites (anterior mediastinum and pineal gland). "Follistatin was expressed predominantly in non-seminomas and spermatocytic seminomas." (PMID 9365168, 1997).
skin cancer (1 paper, 2023). "While FST appears to be the major factor predisposing to skin cancer in our collective, the MC1R genotype seems to predominate over FST: in a multivariate analysis, the MC1R genotype, but not the FST, remained significant." (PMID 36765822, 2023).
Stroke (1 paper, 2014). Sudden impairment of blood flow to a part of the brain due to occlusion or rupture of an artery to the brain. "The Chinese medicine formulation ISF-1 (also known as Bu-Yang-Huan-Wu-Tang) for post-stroke rehabilitation could increase the expression of growth-regulating protein follistatin by approximately 4-fold." (PMID 25237385, 2014). "Therefore, pharmacological induction of follistatin expression might serve as a new strategy for the treatment of post-stroke and age-related sarcopenia." (PMID 25237385, 2014).
synovitis (1 paper, 2014). Inflammation of a synovial membrane. "Synovitis induced by intra-articular injection of carrageenan was significantly alleviated by preinjection with follistatin." (PMID 25574420, 2014).
testicular germ cell tumours (1 paper, 1997). "Therefore, the expression of inhibin/activin subunits, of activin receptors and of the activin-binding protein follistatin was studied in testicular germ cell tumours, using RNAase protection assays." (PMID 9365168, 1997).
thymoma (1 paper, 2019). A neoplasm arising from the epithelial cells of the thymus. "Conversely, we detected highest Follistatin serum concentrations in patients with TCs, which were significantly higher compared to thymomas (p = 0.021) and volunteers (p = 0.002)." (PMID 31757999, 2019). "There were no semiquantitative differences in Follistatin staining intensity between thymomas and TCs." (PMID 31757999, 2019). "In particular, 75% of all TCs displayed absent Follistatin in nuclei, whereas absent nuclear Follistatin expression was found in 19% of all thymomas (p = 0.053)." (PMID 31757999, 2019). "There was a trend towards absent nuclear Follistatin expression in TCs compared to thymomas." (PMID 31757999, 2019).
thyroid cancer (1 paper, 2023). "Since increased follistatin serum levels were found in thyroid cancer patients and correlated with advanced tumor aggressiveness, a strong reduction of follistatin secretion may support a role for macrophages in the reduced invasion and migration of C3948 cancer cells observed." (PMID 37686663, 2023).
Tumor Lysis Syndrome (1 paper, 2024). a group of metabolic abnormalities that can occur as a complication during the treatment of cancer, most commonly after the treatment of lymphomas and leukemias. "Our study revealed that urinary follistatin exhibited a generally analogous pattern to KIM-1, with heightened sensitivity in specific scenarios such as renal transplantation and tumor lysis syndrome." (PMID 38534369, 2024).
viral hepatitis C (1 paper, 2015). "Abnormal levels of serum activin-A and follistatin have been documented in several liver pathologies including viral hepatitis C. Additionally, CHC and Peg-INF-α based therapy have been recently shown to modulate the serum concentrations of both proteins." (PMID 25969625, 2015).